OR52M1 (olfactory receptor family 52 subfamily M member 1)
Description:
Odorant receptor.
Synonyms: OR52M1P; OR11-11; OR52M3P
Tractability: Small molecule: it belongs to a druggable protein family. Antibody: UniProt places it where antibodies can reach, with medium confidence; UniProt predicts a signal peptide or a membrane-spanning region; its Gene Ontology location is reachable by antibodies, with medium confidence.
Gene: Protein-coding gene on chromosome 11 (4,545,191 to 4,546,144, forward strand). Ensembl gene ENSG00000197790.
Subcellular location: Cell membrane
Pathways (Reactome):
Sensory Perception: Expression and translocation of olfactory receptors
Gene Ontology:
Molecular function: olfactory receptor activity; G protein-coupled receptor activity
Biological process: detection of chemical stimulus involved in sensory perception of smell; G protein-coupled receptor signaling pathway; nervous system process
Cellular component: plasma membrane; membrane
Genetic constraint (gnomAD): Loss-of-function variants: 12 observed, 8.18 expected, observed/expected ratio (o/e) 1.47, 90% interval 0.91 to 1.92. That is too few expected variants to judge how well the gene tolerates losing a copy. Missense variants: 558 observed, 410.46 expected, observed/expected ratio (o/e) 1.36, 90% interval 1.27 to 1.46. Synonymous variants: 227 observed, 157.36 expected, observed/expected ratio (o/e) 1.44, 90% interval 1.29 to 1.61.
Homologues: Orthologues: chimpanzee OR52M1 (98% identical), macaque OR52M1 (94% identical), rat Or52m1 (91% identical), mouse Or52m1 (90% identical), guinea pig OR52M1 (87% identical), pig OR52M1 (86% identical), tropical clawed frog or52m1 (53% identical). Paralogues in human: OR52L1 (51% identical), OR52R1 (51% identical), OR52A5 (50% identical), OR52B2 (49% identical), OR52E2 (49% identical), OR51G2 (49% identical), OR52D1 (49% identical), OR52K1 (49% identical), OR52K2 (49% identical), OR51E1 (48% identical), OR51E2 (48% identical), OR52J3 (48% identical), and 39 more.
Diseases named in the same sentence as OR52M1 in open-access papers:
OR52M1 is named in the same sentence as 1 disease in open-access papers, as found by Europe PMC text mining. Sharing a sentence is not in itself a finding about the gene and the disease. The quoted sentences say what the papers report.
autism (1 paper, 2022). Persistent deficits in social interaction and communication and interaction as well as a markedly restricted repertoire of activity and interest as well as repetitive patterns of behavior. "The detection of variants within the OR11H12 gene encoding an olfactory receptor is also not surprising, as rare and common variants in at least several OR genes have been reported in association with autism, such as OR2M4, OR2T10, and OR52M1." (PMID 35627305, 2022).